IL18 (interleukin 18)
Diseases named in the same sentence as IL18 in open-access papers (continued):
Sharing a sentence is not in itself a finding about the gene and the disease.
pulmonary hypertension (8 papers, 2015 to 2024). Increased pressure within the pulmonary circulation due to lung or heart disorder. "In addition, lung-specific overexpression of IL-18 in mice was also shown to associate with pulmonary hypertension, while IL-18 suppression attenuates that blood pressure elevation and IL-18 receptor deficiency results in protection against a respiratory insult such as cigarette smoke." (PMID 33494430, 2021). "In this study of hypoxic pulmonary hypertension, epithelial derived IL‐18 can be a trigger of pulmonary inflammation and pulmonary hypertension via IL‐6 generation in infiltrating monocytes/macrophages and STAT3 signaling." (PMID 39034131, 2024). "IL-18 and TNF-α are pro-inflammatory cytokines previously reported to be associated with BPD or pulmonary hypertension in preterm infants or experimental models of BPD27–30." (PMID 33888735, 2021). "The ELISA results showed that AS‐IV reduced the levels of IL‐18 and IL‐1β in the serum of rats with pulmonary hypertension, and the inhibitory effect was similar to that of MCC950 and MDL‐28170." (PMID 33295020, 2021). "Caspase‐1 activation and IL‐18 secretion from bronchial epithelial cells might initiate hypoxia‐induced inflammation, leading to pulmonary hypertension." (PMID 39034131, 2024). "Increased levels of proinflammatory cytokines, such as interleukin (IL)‐18, have been shown in patients suffering from chronic lung diseases, who are prone to develop both alveolar hypoxia and pulmonary hypertension." (PMID 39034131, 2024). "Numerous studies have demonstrated that Sil can significantly lower IL-18 levels of burned rat model heart tissue and that Sil treatment can lower NLRP3 expression in the lungs of animals with pulmonary hypertension." (PMID 37636019, 2023). "Interestingly, mice lacking NLRP3 display attenuated pulmonary hypertension and a blunted inflammasome activation with decreased caspase-1, IL-18, and IL-1β levels in response to hypoxia induced pulmonary vasoconstriction." (PMID 31915037, 2020).
respiratory infections (8 papers, 2013 to 2025). "Thus we hypothesized that respiratory infections causes the release of EVs in the airway and that the raised ATP levels, present in respiratory disease, triggers the release of IL-1β/IL-18, neutrophilia and subsequent disease exacerbations." (PMID 24972036, 2014). "This study observed that EVs released during respiratory infections carried and released IL-1b and IL-18, suggesting a mechanism that results in disease exacerbation." (PMID 35382831, 2022). "This is relevant in the context of P. aeruginosa respiratory infections as it has been demonstrated in murine acute P. aeruginosa pneumonia models that IL-1β and IL-18 released upon alveolar macrophage inflammasome activation are deleterious for the host." (PMID 25706389, 2015). "We have also showed that serum level of IL-18 in children with single episode of urticaria and symptoms of upper respiratory infection was increased as compared to healthy subjects." (PMID 24490166, 2013). "In the group with single episode of acute urticaria, in children with symptoms suggestive of upper respiratory infection (n = 21, 53.9%) both serum IL-1RA and IL-18 was significantly higher than in healthy children (P < 0.0001, P < 0.00008, resp)." (PMID 24490166, 2013). "In the group with single episode of urticaria and in children with symptoms of upper respiratory infection, IL-1RA and IL-18 levels were higher than in controls." (PMID 24490166, 2013). "In addition, respiratory infection, whether viral or bacterial, may be responsible for periods of exacerbations, as they drive an increased release of functional EVs which contain pro-inflammatory cytokines IL-1B and IL-18 and result in exacerbated neutrophilia." (PMID 35382831, 2022). "Moreover, in vivo studies with respiratory infection of Staphylococcus aureus have demonstrated that neutralization of NLRP3 improves bacterial clearance, while blocking IL-1β/IL-18 does not." (PMID 36068223, 2022).
systemic sclerosis (8 papers, 2012 to 2024). A chronic disorder, possibly autoimmune, marked by excessive production of collagen which results in hardening and thickening of body tissues. "To reach this objective, we evaluated the presence of caspase-1, lactate dehydrogenase (LDH), the cytokines IL-1β and IL-18, and the association between them in the bronchoalveolar lavage (BAL) of patients with ASSD and systemic sclerosis (SSc)." (PMID 36611853, 2022). "The polymorphisms identified in ACE2 (chrX_15596143), IL-18 (chr11_112014152), IL-18R1 (chr2_103013408), IFNGR1 (chr6_137519588), and IL-2 (chr4_123377482) genes can be considered predisposing factors for the onset of systemic sclerosis." (PMID 38675400, 2024). "For instance, in dermal fibroblasts from patients with systemic sclerosis, the inhibition of CASP1 reduces the collagen deposition and the IL-18 and IL-1β release." (PMID 38786058, 2024).
Thrombosis (8 papers, 2019 to 2023). "We also observed a concomitant increase in the relative expression of NLRP3, caspase-1, interleukin-1β (IL-1β), and interleukin-18 (IL-18) transcripts in the individuals with clinically established venous thrombosis." (PMID 31653092, 2019). "Neutralizing antibodies against SARS-CoV-2 can activate IL-18 and IL-16, myeloid chemotaxis, and activation of lymphocytes, monocytes, and natural killers, which lead to neutrophil activation, hypercoagulation, and thrombosis." (PMID 34858909, 2021). "Three of all the other four combinations to decrease the activation of Thrombosis included targeting TLR4, while the last one relied on the simultaneous blocking of IL-1β and IL-18." (PMID 36261775, 2022). "Subsequent analysis of the Canakinumab Anti-inflammatory Thrombosis Outcome Study revealed that inhibiting IL-1β does not modify the plasmatic levels of IL-18." (PMID 37004526, 2023).
urinary tract infection (8 papers, 2008 to 2023). "Although IL-18 was reported to be a promising marker to predict acute renal injury prior to elevation of serum creatinine, it is probable that the marker was specific to ischemic renal injury rather than urinary tract infections as previously reported." (PMID 26317016, 2013).
ZIKV infection (8 papers, 2016 to 2025). "Our findings showed that ZIKV infection upregulates the expression of IL-18, especially in the third gestational trimester, which can put the pregnancy at high risk." (PMID 35632746, 2022). "We showed that MAIT cell IFNγ production following in vitro ZIKV infection also depended on IL-12 and IL-18." (PMID 29357366, 2018). "Of note, the fact that ZIKV infection leads to the production of IL-18 suggests that the inflammasome is activated during the course of infection." (PMID 27163257, 2016). "Alternatively, FcRγ expression is associated with NK cell proliferation in response to cytokines, which could be driven by IL-2, IL-12, and IL-18, all of which are upregulated in acute ZIKV infection." (PMID 41000887, 2025). "However, MAIT cells from HIV-1-infected subjects had a normal response to direct cytokine stimulation, suggesting that poor IL-12 and IL-18 production in response to ZIKV infection could be responsible for the impaired MAIT cell response in these individuals." (PMID 29357366, 2018). "The results showed that acute ZIKV infection induces more intensive GDF3, NLRP3, IL-1β, and IL-18 expression in the context of pregnancy." (PMID 35632746, 2022). "In conclusion, this study demonstrated that acute ZIKV infection during pregnancy triggers overexpression of the growth factor GDF3 and the inflammasome-related factors NLRP3, IL-1β, and IL-18." (PMID 35632746, 2022). "IPA also predicted many cytokines, including IL-15, IL-27, IL-32, C5, IL-18, and EB13, were significantly up-regulated by ZIKV infection in HSerC." (PMID 32511241, 2020). "Using a qRT-PCR assay, high expression levels of pro-inflammatory cytokine genes, including IL6, IL15, IFNγ, TNFα, CXCL15, IL18, and IL1β, were confirmed in ZIKV-infected placentas, suggesting that ZIKV infection may trigger placental inflammation." (PMID 41263557, 2025). "Serum samples from pregnant (n = 18) and non-pregnant (n = 22) women with acute ZIKV infection were assessed for NLRP3, IL-1β, IL-18, and GDF3 markers through an enzyme-linked immunosorbent assay." (PMID 35632746, 2022). "MAIT cell IFNγ response to ZIKV infection was TCR independent, but IL-12 and IL-18 dependent." (PMID 29357366, 2018).
adenomyosis (7 papers, 2011 to 2026). The growth of endometrial tissue inside the muscular wall of the uterine corpus. "In previous studies, interleukin-18 (IL-18) was found to be possibly related to the pathologic process of adenomyosis." (PMID 39456936, 2024). "To date, there has been little information regarding the nature of IL-18 system in the pathophysiologic mechanism of adenomyosis." (PMID 36354688, 2022). "With CT value quantification and the 2−∆∆Ct method, significant down-regulation of IL-18BP in myometrium compared to eutopic endometrium (p < 0.05) implicates that IL-18 system acts as a local immune regulator at the level of EMI in adenomyosis." (PMID 36354688, 2022). "The expression of endometrial IL-18R and the ratio of IL-18 antagonist to agonist are significantly higher in patients with adenomyosis than the healthy control." (PMID 36354688, 2022). "We suggest that altered IL-18 system expression contributes to immunological dysfunction and junctional zone disturbance in women with adenomyosis." (PMID 36354688, 2022). "The previous study showed a higher ratio of IL-18 antagonist to agonist in patients with adenomyosis than in healthy controls, indicating that dysregulation of IL-18 system possibly contributed to the pathogenesis of adenomyosis." (PMID 36354688, 2022). "Moreover, nonsteroidal anti-inflammatory drugs (NSAIDs) provide partial symptomatic relief in adenomyosis, further implicate inflammatory pathways, such as IL-18 and TLR4, in adenomyosis pathogenesis." (PMID 41209546, 2025). "It has been suggested that increased production of IL18 may disrupt immunological processes in the myometrium and may be involved in the development of adenomyosis." (PMID 39639230, 2024). "The present study was designed to determine whether IL-18 expresses in the ectopic and/or eutopic endometrium, and to compare IL-18 system expression among the eutopic endometrium, ectopic endometrium, and corresponding myometrium in patients with adenomyosis." (PMID 36354688, 2022). "Disruption of the EMI either directly by endometrial factors or indirectly by an IL-18-mediated immune response may contribute to a local immune-modulating cytokine network in the pathogenesis of adenomyosis." (PMID 36354688, 2022). "Elucidation of IL-18 system modulating at the level of EMI may provide new insights into the pathogenesis of adenomyosis." (PMID 36354688, 2022). "We uncovered that mRNA of IL-18 system, including IL-18, IL-18 receptor (IL-18R), and its antagonist, IL-18 binding protein (IL-18BP), expressed in eutopic, ectopic endometrium, and corresponding myometrium in patients with adenomyosis." (PMID 36354688, 2022). "However, IL-18-mediated immune response remains obscure in the process of adenomyosis." (PMID 36354688, 2022). "In summary, this study has illustrated the expression of the complete IL-18 system and its regulation at the level of EMI in eutopic, ectopic endometrium, and corresponding myometrium of patients with adenomyosis." (PMID 36354688, 2022). "IL1B, IL18 and TNF were all significantly increased in women with adenomyosis compared with controls (P = 0.002, P = 0.041 and P = 0.022, respectively)." (PMID 35773139, 2022). "For example, patients with adenomyosis have an increased number of macrophages, gamma delta T cells in ectopic and eutopic endometrium, and elevated preinflammatory factors and cytokines (e.g. TNF-α, IL-10, and IL-18) in the uterus and peritoneal fluid." (PMID 21385399, 2011).
ankylosing spondylitis (7 papers, 2016 to 2025). An autoimmune chronic inflammatory disorder characterized by inflammation in the vertebral joints of the spine and sacroiliac joints. "Based on our ELISA data, we observed significant increases in multiple pro-inflammatory factors (IL-17, IL-23, TNF-α, IL-1β, and IL-18) in the serum of mice with ankylosing spondylitis (AS) compared to the control group (p < 0.05)." (PMID 39857593, 2024).
bone cancer (7 papers, 2015 to 2025). A primary or metastatic malignant neoplasm affecting the bone or articular cartilage. "Microglia NFAT1‐p38 signaling contributes to bone cancer pain through IL‐18‐mediated central sensitization in spinal microglia." (PMID 39957627, 2025). "The effect of pharmacologic intervention of spinal NFAT1/IL‐18 signaling on bone cancer pain was the primary outcome." (PMID 39957627, 2025). "To evaluate the microglial mechanism of NFAT1/p38 in bone cancer pain, we examined changes in the expression of the proinflammatory cytokine IL‐18 in the spinal dorsal horn through the spinal blockade of NFAT1 or p38." (PMID 39957627, 2025). "Inhibition of the spinal P2X7R/p38/IL-18 pathway resulted in a reduction of pain behaviors in late-stage bone cancer." (PMID 40717979, 2025). "We investigated the effects of NFAT1 on pain behavior in LLC‐induced bone cancer and on the release of the downstream proinflammatory cytokine IL‐18 through the p38 MAPK signaling pathway." (PMID 39957627, 2025). "Inhibiting P2X7R in spinal microglia can alleviate bone cancer pain by reducing spinal nerve hyperactivity through the p38/IL-18 pathway." (PMID 40717979, 2025). "In contrast, the proinflammatory function of IL-18 has been well characterized, with elegant studies demonstrating its contribution to neuropathic and bone cancer pain by regulating glial function." (PMID 36369350, 2022). "This study aimed to test the hypothesis that nuclear factor of activated T cells 1 (NFAT1) signaling contributes to bone cancer pain by regulating interleukin (IL)‐18 expression in spinal microglia." (PMID 39957627, 2025). "Additionally, IL‐18 signaling contributed to bone cancer pain by regulating neuronal activity through the NMDA receptor and Ca2+‐triggered signals." (PMID 39957627, 2025). "NFAT1/IL‐18 pathway‐mediated microglia–neuron interactions may facilitate and improve processing of bone cancer pain." (PMID 39957627, 2025). "Mechanisms underlying L-THP-induced attenuation of bone cancer pain may be partially through inhibiting microglial cells activation, as well as proinflammatory cytokines TNF-α and IL-18 releasing, in spinal cord." (PMID 26819501, 2015). "However, the role of IL‐18 signaling in bone cancer pain is unclear." (PMID 39957627, 2025). "Bone cancer pain shares common features of both inflammatory and neuropathic pain, and inhibition of P2X7R in spinal microglia can reduce bone cancer pain by reducing spinal nerve hyperactivity through the p38/IL‐18 pathway." (PMID 37950524, 2023). "Repeated intrathecal injection of IL‐18 BP effectively attenuated the tumor‐induced activation of NR2B and the subsequent Ca2+‐dependent signals as well as tumor‐induced bone cancer pain, suggesting that NFAT1/IL‐18 could regulate synaptic plasticity by interacting with NMDA receptors." (PMID 39957627, 2025).
brain tumors (7 papers, 2010 to 2023). "Furthermore, a SIN DNA replicon encoding the human gp100 and mouse IL-18 was evaluated in B16-gp100 implanted brain tumor models in mice." (PMID 34696295, 2021). "Related to brain tumors, co-expression of human gp100 and mouse interleukin-18 (IL-18) from SIN DNA replicons in mice with implanted B16-gp100 brain tumors showed both protective and therapeutic efficacy." (PMID 36986808, 2023). "SIN DNA replicons expressing human gp100 and mouse IL-18 were intramuscularly injected into mice implanted with B16-gp100 brain tumors." (PMID 36140364, 2022). "In another approach, SIN DNA replicons expressing the human gp100 and mouse IL-18 were intramuscularly administered to mice bearing B16-gp100 brain tumors." (PMID 35495626, 2022). "In another approach, intratumoral injection of DCs transduced with SFV particles expressing interleukin-18 (IL-18) in combination with recombinant IL-12 protein therapy, elicited Th1-type immune responses and provided anti-tumor immunity in a B16 brain tumor mouse model." (PMID 34696295, 2021). "Moreover, dendritic cells (DCs) transduced with SFV particles expressing interleukin-18 (IL-18) were administered intratumorally into mice bearing B16 brain tumors in combination with systemic administration of IL-12." (PMID 32698494, 2020). "In the context of brain tumors, immunization with SIN DNA expressing human gp100 and interleukin-18 (IL-18) enhanced both protective and therapeutic effects on malignant brain tumors." (PMID 30857255, 2019).
chronic heart failure (7 papers, 2010 to 2026). "Linggui Zhugan Decoction significantly inhibited the elevation in the levels of serum IL6, IL18, and IL-10 of the chronic heart failure rats." (PMID 32508942, 2020).
chronic hepatitis B (7 papers, 2008 to 2025). "However, the real roles of IL-18 gene promoter polymorphisms in the pathogenesis of developing chronic hepatitis B needs to be further investigated within large population from different ethnic groups and geographic regions." (PMID 25031585, 2014). "It is suggested that IL-18 genotype -607 A/A is associated with susceptibility to chronic hepatitis B. Furthermore, the carriage of allele C at position -137 may play a protective role in the development of chronic HBV infection." (PMID 25031585, 2014). "In this study, the expression AIM2, and its downstream cytokines, caspase-1, IL-18 and IL-1β, in liver tissue of patients with chronic hepatitis B and C (CHB, CHC) were investigated." (PMID 26290184, 2015). "Meanwhile, it has been shown that in vitro IL-18 can improve the peripheral blood monocytes (PBMC) from chronic hepatitis B patients to produce a high level of IFN-γ." (PMID 25031585, 2014). "Taking this evidence into consideration, possible role of the SNPs of IL-18 gene-promoter region in the progression of chronic hepatitis B were investigated in a number of recent studies." (PMID 25031585, 2014). "Genomic research in this area uncovered SNPs in the interleukin-18 (IL-18) gene and its promoter, which were associated with chronic hepatitis and development of HCC among chronic hepatitis B patients, respectively." (PMID 18654621, 2008).
chronic hepatitis C (7 papers, 2018 to 2025). "A growing body of evidence has suggested that proinflammatory cytokines (IL-1β and IL-18) play a substantial role in both acute and chronic hepatitis C." (PMID 30728751, 2019). "It is also documented that liver-infiltrating T cells from chronic hepatitis C patients produced IFN(interferon)-γ, apoptotic hepatocytes released IL-1α, and macrophages exposed to HCV secreted IL-1β and IL-18." (PMID 36901973, 2023). "It is also documented that liver-infiltrating T cells from chronic hepatitis C patients produce IFN-γ, apoptotic hepatocytes release IL-1α, and macrophages exposed to HCV induce IL-1β and IL-18 secretion." (PMID 35887291, 2022).
dermatomyositis (7 papers, 2012 to 2025). Dermatomyositis (DM) is a type of idiopathic inflammatory myopathy characterized by evocative skin lesions and symmetrical proximal muscle weakness. "IL-18 distinguishes dermatomyositis skin inflammation from cutaneous lupus erythematosus lesions." (PMID 32644977, 2020). "In dermatomyositis, IL1B and IL18 protein levels are elevated in serum, and gene expression levels are also increased in muscle tissue." (PMID 40080076, 2025). "Yin Xi’s research group reported that compared to healthy controls, patients with polymyositis (PM) and dermatomyositis (DM) showed elevated levels of NLRP3, IL-1β, and IL-18 mRNA in muscle fiber tissues, as well as increased expression of NLRP3 and caspase-1 p20 protein subunit." (PMID 39723212, 2024).